NGF (nerve growth factor)
Diseases named in the same sentence as NGF in open-access papers (continued):
Sharing a sentence is not in itself a finding about the gene and the disease.
Alzheimer disease (continued). "Changes in the levels of NGF in the CNS appear also to play an important role in the context of neurodegenerative disorders such as Alzheimer disease (AD)." (PMID 22474604, 2012). "In particular, this study addresses the question whether the intranasal administration of NGF-based molecules to Familial Alzheimer Disease-based mouse models might exert neuroprotection and prevent the progression of the neuropathological and behavioral deficits." (PMID 22666365, 2012). "From a translational standpoint, the action of NGF on cholinergic neurons of the basal forebrain and on sensory neurons in dorsal root ganglia first gained researcher’s attention, in view of possible clinical use in Alzheimer’s disease patients and in peripheral neuropathies respectively." (PMID 23190582, 2012). "However Cuello and colleagues, have provided evidence that the conversion of proNGF to mature NGF is diminished in Alzheimer’s disease, is accompanied by increased degradation of mature NGF, and that this is likely to be an initiating factor in the degeneration of the cholinergic neurons." (PMID 22654716, 2011). "In the case of Alzheimer’s disease, a chimeric AAV2/5 vector with the AAV2 genome and the AAV5 capsid structure has been applied for the expression of the nerve growth factor (NGF)." (PMID 36992407, 2023). "Currently one of these small-molecule NGF mimetics, the P75NTR binding molecule LM11A-31, is under evaluation in clinical trials in Alzheimer’s disease." (PMID 35360160, 2022). "Basal forebrain cholinergic neurons are dependent on nerve growth factor (NGF) for growth and survival and these cells are among the first to degenerate in Alzheimer’s disease (AD)." (PMID 35557841, 2022). "In animal models of the disease and in humans, the levels of NGF and BDNF follow different trajectories in brain areas affected in Alzheimer’s disease." (PMID 30939824, 2019). "Neurotrophins like nerve growth factor (NGF) and brain-derived neurotrophic factor (BDNF) are known to play an important role in aging and development of neurodegenerative diseases such as Alzheimer’s disease and AMD." (PMID 30871541, 2019). "We have previously shown that the expression of pro-nerve growth factor (proNGF) was significantly increased, nerve growth factor (NGF) level was decreased, and the expression of p75NTR was enhanced in Alzheimer’s disease (AD) hippocampal samples." (PMID 31430874, 2019). "The current review summarizes the pathobiology of nerve growth factor (NGF) and its cognate receptors during the progression of Alzheimer’s disease (AD)." (PMID 31312116, 2019). "In this article, we provide now stringent evidence that microglia are target cells for NGF, both in vitro and ex vivo and that the activity carried out by this neurotrophin on microglial cells might result neuroprotective and anti‐inflammatory in the context of Alzheimer's disease." (PMID 29473218, 2018). "In this article, we have provided stringent evidence that microglia are target cells for NGF—both in vitro and ex vivo—and that the activity carried out by this neurotrophin might result neuroprotective and anti‐inflammatory in the context of Alzheimer's disease‐related insults." (PMID 29473218, 2018). "It’s been demonstrated that pro-NGF is copious in brains of patients with Alzheimer’s disease and this increase may reflect either an active role for proNGF or posttranslational disorders in NGF biosynthesis that reduce the processing of pro-NGF to NGF in Alzheimer’s disease." (PMID 28068360, 2017). "The nerve growth factor (NGF) and brain-derived neurotrophic factor (BDNF) have been widely studied with respect to their role in the pathogenesis of Alzheimer’s disease." (PMID 28974056, 2017). "Changes in NGF and BDNF levels in the serum have been reported for central neurodegenerative diseases such as Alzheimer’s disease and Parkinson’s." (PMID 28068360, 2017).
Alzheimer disease (continued). "In particular there have been a number of studies on the involvement of nerve growth factor (NGF) and brain derived neurotrophic factor (BDNF) in the development of Alzheimer’s disease." (PMID 22654716, 2011). "Moreover, dysfunctions in the mechanisms driving nerve-growth factor (NGF) retrograde transport from the hippocampus to the basal forebrain are responsible for a prominent degeneration of basal forebrain cholinergic neurons in adult Ts65Dn mice, which is also a hallmark of the Alzheimer's disease." (PMID 21766040, 2011). "This suggests that rTMS may improve cognitive function, depression, psychiatric disorders, and Alzheimer’s disease in patients by upregulating serum BDNF and NGF levels." (PMID 40109842, 2025). "Combining NGF-nanoparticles with NSC transplantation has shown significant improvements in learning and memory functions in rats with Alzheimer’s disease, replenishment of basal forebrain cholinergic neurons, and mitigation of neuronal death following experimental ischemic stroke." (PMID 40153582, 2024). "In summary, NGF was deemed safe, and no long-term adverse effects were observed in six patients with mild Alzheimer’s disease after 22 months of treatment." (PMID 38276526, 2023). "Indeed, the proNGF/NGF balance—though not related to microglia cells in particular—has been heavily implicated in the development of neurodegenerative disorders: in the cortex of Alzheimer’s disease patients, proNGF levels are increased and there is a striking reduction of TrkA expression." (PMID 35681529, 2022). "It is of note that attempts to ablate specific cholinergic neurons with a DTx model for Alzheimer’s disease were not successful to achieve an Alzheimer phenotype, although an NGF-DTx conjugate was directly injected into the forebrain." (PMID 34502404, 2021). "Considering that MMP causes the production of mature neurotrophins, we can speculate that Cu2+ and its complex with NGF mimetic peptides contribute to counteract the differential deregulation of NGF and BDNF found in Alzheimer’s disease." (PMID 30939824, 2019). "In Alzheimer’s disease, chronic inflammation in the brain exacerbates the pathological condition and cognitive decline because inflammation is toxic to neurons and suppresses the production of neurotrophic factors such as BDNF, GDNF and NGF." (PMID 25760987, 2015). "Nerve Growth Factor (NGF) has a considerable therapeutic potential for Alzheimer's disease (AD), not merely as a long-lasting cholinergic maintenance and neuroprotective agent, but also as a direct anti-amyloidogenic factor." (PMID 22666365, 2012). "However, this latent form can be reactivated by NGF deprivation, and NGF promotes viral latency via the TrkA receptor NTRK1, the expression of which is reduced in the Alzheimer's disease brain." (PMID 22254144, 2011). "Our findings indicate that potentiating the activity of NGF at the level of RhoA inactivation and PTP1B activation may represent a new means to combat the noxious effects of Aβ in Alzheimer's disease." (PMID 21294893, 2011). "A model of Down’s syndrome, itself a “model” of Alzheimer’s disease, has virtually no retrograde transport of NGF to the ChBF cell bodies, and it is possible that likewise there is a defect in retrograde transport of NGF in Alzheimer’s disease." (PMID 22654716, 2011). "In addition to playing an important role in Alzheimer’s disease and memory impairment in patients with traumatic brain injury (TBI), brain-derived neurotrophic factor (BDNF) and nerve growth factor (NGF) are extremely important for the rehabilitation of patients with stroke." (PMID 40109842, 2025). "However, NGF-gene delivery therapy did not produce effective outcomes for Alzheimer’s disease patients in the phase II trial." (PMID 38276526, 2023).
Alzheimer disease (continued). "Moreover, in the AD11 mice model, which expresses anti-NGF antibodies specifically in the brain, the lack of mature NGF leads to early inflammation and neurodegeneration that is characteristic to Alzheimer’s disease." (PMID 34440640, 2021). "In the study of the pharmacological mechanism of G9a/GLP on early-onset Alzheimer’s disease in rat, inhibition of G9a/GLP complex could increase the levels of synaptophysin, nerve growth factor (NGF) and BDNF in brain tissues, showing a significant neuroprotective effect on rats." (PMID 34672892, 2021). "Furthermore, an increased NGF concentration in Alzheimer’s disease cortex was found when compared to non-demented controls." (PMID 28068360, 2017). "Furthermore, measurements of NGF protein in Alzheimer’s disease brain unexpectedly showed either significant or non-significant increases in the cerebral cortex and hippocampus, although NGF levels in the ChBF were decreased." (PMID 22654716, 2011). "However, no change was found in NGF mRNA levels in Alzheimer’s disease cerebral cortex and hippocampus compared with normal brain." (PMID 22654716, 2011). "The use of exogenous NGF has been proven to complement the pathological absence of NGF and play the role in promoting the repair of nerve damage in vitro, making NGF a promising therapeutic agent for neural repair in the treatment of CNS diseases such as Alzheimer's disease (SCI)." (PMID 38049878, 2023). "Since NGF does not cross the blood brain barrier, NGF administration through intracerebroventricular (ICV) route has been carried out to evaluate the safety and efficacy of NGF in Alzheimer's disease patients." (PMID 38049878, 2023). "The same trend has been found in subjects with Alzheimer’s disease where BDNF mRNA, its precursor (proBDNF), and mature protein levels significantly decrease, while NGF mRNA does not change, and the NGF precursor molecule proNGF increases." (PMID 30939824, 2019). "Subsequently, studies revaled that NGF exerts a critical protective action on specific brain cells and particularly on the basal forebrain derived neurons undergoing degeneration in Alzheimer disease (AD) and a variety of non-neuronal and neoplastic cells." (PMID 27439311, 2016).
depression (123 papers, 2010 to 2026). "Sedentarism-related inflammatory responses, such as increased interleukin-6 and decreased brain-derived nerve growth factor levels, are recognized as pathological causes of emotional stress and depression." (PMID 40508900, 2025). "According to the neurodegeneration theory, in patients with schizophrenia and depression disorders, the molecular mechanisms of neuroplasticity sometimes manifest as abnormal functions due to NGF deficiency." (PMID 40783715, 2025). "Various clinical studies in human and animals showed an association of low NGF levels with depression compared with healthy controls." (PMID 38362105, 2024). "This suggests that ROI, NGF indices, and the phenome are manifestations of the same underlying core, namely the severity of the illness depression." (PMID 37509019, 2023). "Surprisingly, whereas depression is related to lower peripheral NGF levels, more “positive” emotional states, such as love, are associated with higher NGF levels." (PMID 37509019, 2023). "Many diseases of nervous system are associated with NGF insufficiency, especially neurodegenerative diseases, for example, depression and Alzheimer's disease." (PMID 23878590, 2013). "In addition to BDNF, depression and neurodegeneration are associated with other decreased neurotrophic factors, like neurotrophic factor-α1 (NF-α1) and nerve growth factor." (PMID 38038373, 2024). "The possible biological mechanisms linking depression with dementia include vascular disease, changes in glucocorticoid levels, hippocampal atrophy, increased amyloid β plaque deposition, inflammatory changes, and nerve growth factor deficiency." (PMID 35221992, 2022). "Like BDNF, NGF seems to be negatively associated with depression and suicide." (PMID 30767081, 2019). "Indeed, low expression of NGF is one of the causes for patients suffering from dementia or depression." (PMID 29681968, 2018). "Lowered NGF (p = 0.003) and the NGF/NT ratio (p < 0.001) are highly significantly and inversely associated with the severity of the current depression phenome, conceptualized as a latent vector extracted from the current severity of depression, anxiety, and suicidal behaviors." (PMID 37509019, 2023). "In addition to BDNF, also IGF-1, FGF-2, and NGF have been implicated in depressive disorders." (PMID 35886944, 2022). "In addition to CRF, neurotrophins (brain-derived neurotrophic factor (BDNF) and nerve growth factor (NGF)) may be involved in the pathophysiology underlying OAB coexisting with depression." (PMID 30155683, 2019). "The onset of depression has been associated with structural changes in the hippocampus and a decrease in BDNF, GDNF, and NGF." (PMID 40260589, 2025). "NGF (nerve growth factor) is consistently reduced in depression, correlating with symptom severity and remaining unchanged by treatment." (PMID 40428308, 2025). "In certain regions of the brain in a depression model, e.g., the prefrontal cortex and hippocampus, NGF downregulation is accompanied by the suppression of the cAMP/cAMP response element binding protein (CREB), PI3K/AKT, and MAPK/ERK pathways." (PMID 40783715, 2025). "While the TrkA is traditionally associated with Nerve Growth Factor (NGF), is believed to interact with BDNF and NT4 pathways as well, suggesting a broader role in depression’s neurobiology." (PMID 38963553, 2024). "Inhibition of the expression of brain-derived neurotrophic factor (BDNF) and nerve growth factor (NGF) in the peripheral nervous system is related to abnormal neural function in the brains of patients with depression." (PMID 39114351, 2024). "The most occurrences of author keywords, after excluding the core keywords related to the search query, were neuropathic pain, microglia activation, depression, nerve growth factor, spinal cord, animal study, TrkB, and inflammation." (PMID 38617040, 2024).
depression (continued). "IL-6 and CRP are the two most commonly increased inflammatory factors, and the nerve growth factor (NGF) is the most commonly decreased factor in depression and schizophrenia." (PMID 39058106, 2024). "NGF is involved in the growth development, survival of neurons, maintenance, and proliferation, but its role in depression is still controversial." (PMID 38707461, 2024). "Our study’s findings of reduced NGF and BDNF expression align with both clinical and animal research, which propose that depression is linked to neuronal degeneration in the hippocampus due to low neurotrophin levels." (PMID 39684342, 2024). "The same holds true for NGF, another important member of neurotrophin, which is dysregulated in the pathophysiology of depression." (PMID 36979937, 2023). "Neurotrophins best studied in the context of OAB and depression, i.e., NGF and BDNF, are responsible for sensory afferent nerve plasticity." (PMID 36835228, 2023). "Ginger also shows AD effects by improving the NGF-ERK-CREB signaling system in rat models of depression." (PMID 37631092, 2023). "NGF, the zNGF-zNT and zNGF-zGF ratios were significantly lower in patients with depression than control subjects." (PMID 37509019, 2023). "Fluoxetine and lithium are known to treat depression by upregulating NGF protein levels in the hippocampus." (PMID 36986674, 2023). "In a study examining the effects of NGF on depression, NGF improved depression-like behaviors like fluoxetine and amitriptyline, suggesting NGF is involved in the pathogenesis of depressive symptoms and the response to antidepressant treatment." (PMID 37089920, 2023). "As a result, NGF levels appear to be a sensitive indicator of the emotional state of depression and suicidal behaviors as well." (PMID 37509019, 2023). "In our investigation, we discovered that lower NGF levels were inversely related to the intensity of the depressive phenome, which included depression, anxiety, and suicidal behaviors (rated during the previous month)." (PMID 37509019, 2023). "The herbal mixture of Sesami Semen Nigrum and Longan Arillus exhibits AD effects in rat models of depression through a mechanism related to the NGF-induced signal transduction system." (PMID 37631092, 2023). "NGF is an essential factor for neuroregeneration, and NGF levels are significantly lower in major depression." (PMID 36979839, 2023). "The study aimed to investigate the effects of multi-strain probiotic supplementation on serum levels of IL-6, BDNF, nerve growth factor (NGF), and aspects of mental health, including depression, fatigue, and pain." (PMID 38137679, 2023). "A new insight has been introduced into the critical role of NGF activation in brain cells in depression." (PMID 36979839, 2023). "For instance, preclinical studies have demonstrated positive results regarding central IFNγ and NGF for depression, as well as peripheral IL-10 for mania." (PMID 37240605, 2023). "IL-1, TNFα, IFNγ, NGF, or microglia activation in depression, as well as IL-4, TNFα, and IL-10 in mania, were normalized by celecoxib in preclinical studies." (PMID 37240605, 2023). "MBCT combined with pharmacotherapy contributes to improve patients' psychological state and compliance and increases the serum levels of BDNF and NGF preventing the recurrence of depression." (PMID 35069013, 2022). "After MBCT, the serum levels of BDNF and NGF in patients with depression were 88.47 ± 23.65 (ng/mL) and 93.29 ± 22.62 (ng/mL), respectively." (PMID 35069013, 2022). "Results of ELISA revealed that the serum levels of BDNF and NGF were remarkably increased in patients with depression after MBCT (P < 0.001)." (PMID 35069013, 2022). "Analysis of nerve growth factor (NGF) in peripheral blood showed its decrease in patients with depression compared to healthy controls." (PMID 35163141, 2022). "In future research, the extra role of NGF in the development of depression and psoriasis should be clarified." (PMID 35054853, 2022).